CXCL9 (C-X-C motif chemokine ligand 9)
Diseases named in the same sentence as CXCL9 in open-access papers (continued):
Sharing a sentence is not in itself a finding about the gene and the disease.
gastric cancer (29 papers, 2010 to 2025). A primary or metastatic malignant neoplasm involving the stomach. "In the comparison of metabolite interference group and M1 group marker proteins in gastric cancer cells, there were significant differences in IL-6, CXCL9, CXCL10 and CXCL11." (PMID 39991579, 2025). "Previous research on gastric cancer showed that the activation of the CXCL9/CXCR3 axis upregulated the expression of PD-L1 through the STAT and PI3K-Akt pathways." (PMID 38957805, 2024). "Increased CXCL9 expression in gastric cancer leads to decreased proliferation and metastasis of gastric cancer cells." (PMID 35292033, 2022). "Clinical examination of gastric carcinoma samples revealed that CXCL9 was substantially expressed in highly immunogenic tumors and associated with favorable survival outcomes." (PMID 36090326, 2022). "A constructed miRNA-mRNA network showed that CXCL5, CXCL9, and CXCL10 are target genes of miR-588, and high expression of miR-588, CXCL5, CXCL9, and CXCL10 is associated with the prolonged survival in gastric cancer patients." (PMID 34283058, 2021). "Clinical studies on gastric cancer samples showed that CXCL9 was positively correlated with better patients prognosis." (PMID 34367971, 2021). "It confirms the risk of gastric cancer induction by chronic hepatitis B infection, which may be associated with the TLR signaling pathway mediated by CXCL9 and COL6A2." (PMID 38579038, 2024). "There is a lncRNA RP11-1094M14.8/miR-1269a/CXCL9 axis in gastric cancer." (PMID 35252180, 2022). "It has been reported that CXCL9/10/11 is a regulator of PD-L1 expression in gastric cancer." (PMID 34422627, 2021). "In addition, the RP11-1094 M14.8/miR-1269a/CXCL9 axis is a potential prognostic marker for gastric cancer with different degrees of immune cell infiltration." (PMID 33750326, 2021). "CXCL9, CXCL10 and CXCL11 have especially been considered as IFN-γ response cytokines and have been reported to modulate the expression of PDL-1 in gastric cancer cells." (PMID 36766722, 2023). "Plasma levels of IL-8, CXCL9, and CXCL10 were greatly increased in patients with gastric cancer, while being decreased after surgery." (PMID 36612163, 2022). "In gastric cancer specimens of immunotherapy patients, lncRNA RP11-1094M14.8 up-regulated the expression of CXCL9 by inhibiting miR-1269a, thereby promoting CXCL9-mediated lymphocyte infiltration into the lesion and inhibiting tumor growth." (PMID 35252180, 2022). "We investigated the effect of T-DXd on the expression of HLA class I and CXCL9/10/11, T-cell chemoattractants, in HER2-positive human gastric cancer (GC) cells." (PMID 34413454, 2021). "Additionally, 2 Gy of IR increased T lymphocyte recruitment by increasing CXCL9 and CXCL10 levels in AGS-EBV human gastric cancer cells." (PMID 37048082, 2023). "Chemokine gene expression signatures including CCL5, CXCL9, CXCL10, and CXCL11 were reported that could accurately predict anti-PD-1 immunotherapy response for patients with head and neck squamous cell carcinoma and gastric cancer." (PMID 32316408, 2020). "CCL20/MIP-3α, TIMP1, IL8, PDGFR-B, CCL3/MIP-1α and CXCL9/MIG were significantly elevated in the plasma from the gastric cancer patients compared to the plasma from individuals with no visible upper gastro-intestinal pathology or those with benign lesions in stomach." (PMID 21092330, 2010). "In addition, we have shown some of the proteins (CCL20/MIP-3α, TIMP1, IL8, PDGFR-B, CCL3/MIP-1α and CXCL9/MIG) to be detected at a higher level in the plasma from gastric cancer patients than in patients with non-malignant gastric conditions or with normal gastric mucosa." (PMID 21092330, 2010). "IL8, CXCL9/MIG, CCL3/MIP-1α, CCL20/MIP-3α, PDGFR-B and TIMP1 plasma levels were significantly different between the non-malignant group and the gastric cancer group." (PMID 21092330, 2010).
gastric cancer (continued). "In addition, median plasma levels of IL8, CXCL9/MIG, CCL3/MIP-1α, CCL20/MIP-3α, PDGFR-B and TIMP1 proteins were significantly different between the non-malignant group and the gastric cancer group." (PMID 21092330, 2010).
colitis (28 papers, 2008 to 2025). Inflammation of the colon. "Matrix metalloproteinase (MMP)-10, IL-17A, FGF-19, IL-10, and CXCL9 were increased in patients with exclusive colonic inflammation, that is, UC and colonic CD, compared to patients with exclusive ileal inflammation, that is, ileal CD." (PMID 39495605, 2025). "The gene expression of Cxcl9 was higher in all colitis groups compared to the control group (HβG−) after both 3 and 7 days of TNBS administration without any dietary intervention effect." (PMID 35163326, 2022). "On the other hand, colitis rats receiving feed with high-molar-mass oat beta-glucan (CβGh+) resulted in higher expression of only four genes (Ccl19, Ccr4, Ccr8, Cxcl9)." (PMID 35163326, 2022). "Administering FNDC4 to mice with DSS-induced colitis resulted in downregulation of expression of the proinflammatory chemokines Cxcl9 and Cxcl10 (Ip10), consistent with the in vitro data in macrophages." (PMID 27066907, 2016). "As with these innate immunity cells, neutrophils are compartmentalized in the MLN and tightly regulated to differentially express CXCL9 and CXCL11, CXCR3 and Th1-associated cytokines during Mycobacteria-mediated colitis." (PMID 18533024, 2008). "At the molecular level, CXCL9 has been shown to inhibit the reconstitution of the intestinal mucosa after injury and to control E. coli overgrowth through the pyruvate dehydrogenase-encoding aceE gene in a DSS-induced colitis model." (PMID 37645250, 2023). "Importantly, increased Th1 cells within the colon is consistent with recent findings where CXCR3 and its ligands CXCL10/CXCL9 were shown to be enhanced within the colon during immunotherapy-induced colitis." (PMID 36173679, 2022). "After 7 days of induced colitis, upregulation of the expression of 22 genes (Ccl2, Ccl3, Ccl4, Ccl5, Ccl6, Ccl7, Ccl12, Ccl17, Cxcl1, Cxcl2, Cxcl6, Cxcl9, Cxcl11, Ccr1, Ccr2, Ccr3, Ccr5, Ccr8, Cxcr2, Csf3, Osm, and Spp1) was observed in the CβG− group compared to the HβG- control group." (PMID 35163326, 2022). "Thus, in a combined model of Mbd2−/− colitis susceptibility (Graphical Abstract), we speculate that at the onset of intestinal inflammation, the Mbd2 deficient epithelium leads to further intestinal damage, through Cxcl9 driven CD8+ T-cell recruitment and EC-MHC-II upregulation." (PMID 32117307, 2020). "We found that there were 15 analytes upregulated in both DSS and C. rodentium colitis, including innate immune cell-associated cytokines (G-CSF, IL-1β, TNF-α, LIF, and IL-6), chemokines (CCL2, CCL5, CCL11, CXCL2, CXCL8, CXCL9, MIP-1α, and MIP-1β), and Th1 (IFN-γ) and Th17 (IL-17) cytokines." (PMID 30972302, 2019). "C. rodentium-infected mice depleted of CXCL9 had (i) increased evidence of colitis in the cecum, which was shrunken and partially emptied; (ii) shortening and thickening of the colon; (iii) increased incidence of watery stool; and (iv) hematomas along the length of the cecum and colon." (PMID 25643352, 2015). "CXCL-9 mRNA was upregulated in colitis in B6 mice, but the effect of C3aR on the expression of this cytokine was difficult to interpret, as B6 WT and C3ar-/- mice had different basal levels of CXCL-9 mRNA." (PMID 23638016, 2013). "Transcription levels of Cxcl9, Ccl3, Ccl4, and Ccl5, which facilitate effector CD8+ T-cell extravasation into tissues, were significantly lower in the tumors of colitis mice than in that of normal mice." (PMID 37605139, 2023). "This is partly evidenced by an elevated expression of T-cell chemoattractants such as CXCL9, CXCL11, and CCL21 in colonic epithelial cells in piglets with DSS-induced colitis." (PMID 35898495, 2022). "The expressions of ICAM-1, IL-1β, IL-16, CXCL10, MCP-1, CXCL9, CXCL12, and TIMP-1 were greatly reduced in MSC-EX-treated colitis group compared with those in the PBS-treated colitis group." (PMID 28842625, 2017).
colitis (continued). "CXCR3 interactions with CXCL9, CXCL10 and CXCL11 are important for the selective homing of Th1 effectors cells, which mediate mucosal immunity, inflammation, and colitis." (PMID 18533024, 2008). "Our results also suggest plasmacytoid > > myeloid DCs express CXCL9 and CXCL11, but less CXCL10 as well as IFN-γ to recruit, differentiate, and expand Th1 cells to mediate colitis." (PMID 18533024, 2008). "In contrast, we noticed a modest decrease in the number of PP CXCR3+, IFN-γ+, CXCL9+ and CXCL11+ NK cells during live Mycobacteria-enhanced colitis." (PMID 18533024, 2008). "In addition, the upregulated expression levels of downstream genes in colitis mice after DVF challenge, including Cxcl9, Cxcl10, IL1β, and Tnf-α, were significantly decreased by typhaneoside." (PMID 38172943, 2024). "In addition, DEGs associated with the immune receptor (Lrrc19), cell chemotaxis (Ccr7, Cxcl1, Cxcl5, Cxcl9, and Cxcl10), and inflammatory response (IL1r11, IL11, Tnf, IL1β, and IL18) were also upregulated in the colonic tissue of colitis mice in DVF group." (PMID 38172943, 2024). "In contrast, it has been reported that IL-26 could protect mice against acute DSS-induced colitis, which is accompanied by reduced expression of TNF, CXCL9, and CXCL10, although its precise role in chronic colitis remains unclear." (PMID 35463017, 2022). "Cytokine protein arrays showed that the levels of several cytokines, including sICAM-1, IL-1β, IL-16, CXCL10, MCP-1, CXCL9, and TIMP-1, were upregulated (≥50-fold) in the colitis-induced PBS-treated group compared with those in the normal healthy control group." (PMID 28842625, 2017). "The numbers of MLN and LP DCs subsets expressing CXCL9 and CXCL11 after the onset of colitis were significantly increased during live Mycobacteria-enhanced colitis than in the other groups with the exception of MLN CXCL10+ myeloid DCs that were elevated following live bacterial challenge." (PMID 18533024, 2008). "PP and MLN DCs expressed elevated levels of CXCL9 and CXCL11, but not CXCL10, during Mycobacteria-enhanced colitis as indicated by their relative mean fluorescent intensities." (PMID 18533024, 2008).
influenza (28 papers, 2008 to 2025). An acute viral infection of the respiratory tract, occurring in isolated cases, in epidemics, or in pandemics; it is caused by serologically different strains of viruses (influenzaviruses) designated A, B, and C, has a 3-day incubation period, and usually lasts for 3 to 10 days. "Meanwhile, CXCL9 (MIG), which is strongly elevated in severe influenza, isinversely correlated with the duration of fatigue in CFS; in other words, higher CXCL9 is linked to shorter fatigue duration." (PMID 40640868, 2025). "Empagliflozin treatment decreased the expression of the inflammatory cytokines IL-1β, IL-6, and CCL2; the percentage of inflammatory monocytes and inducible NO synthase–positive macrophages; and IFN response genes Stat1 and CXCL9 during influenza infection." (PMID 38112660, 2023). "Following influenza infection, aged defects in CXCL9 production impaired NK cell accumulation within the DLN." (PMID 36802099, 2023). "During influenza infection, secretion of CXCL9 and CXCL10 from the inflamed epithelium recruits CD8 T cells expressing CXCR3 chemokine receptors." (PMID 32817719, 2020). "Accordingly, we found increased mRNA expression of Cxcl9 in influenza/MRSA infected Stat2−/− mice compared to WT mice." (PMID 30337919, 2018). "CXCL9, 10, and 11 were the most highly induced chemokines by influenza infection." (PMID 22396727, 2012). "We observed increased expression of Stat1, Stat2, Mx1, Oasl2, CCL2, CCL3, CXCL9, and CXCL10 in influenza-infected hearts and lungs when compared to PBS-treated controls." (PMID 38750107, 2024). "In our study, we found increased expression of CCL2, CCL3, CXCL9, and CXCL10 in the heart following PR8, pH1N1, or H3N2 strains of influenza infection." (PMID 38750107, 2024). "CXCR3 ligands CXCL9, CXCL10 and CXCL11 are highly expressed in the lung in response to influenza as well as M. tuberculosis infection." (PMID 37896952, 2023). "Our study further indicated that rosiglitazone treatment decreased downstream signaling agents STAT1, STAT2, and the ISGs Mx1, CXCL9 and CXCL10 during influenza infection." (PMID 31159430, 2019). "Influenza infection also induces the production of such cytokines as TNFa, IL-1, IL-6, and the mononuclear cell attractant chemokines: CCL-3, CCL-4, CCL-5, CXCL9, CXCL10, and CXCL11 in human monocytes, epithelial cells, and rat alveolar or murine macrophages." (PMID 30037133, 2018). "During influenza infection increased TLR7/8/9 expression is known to correlate with elevated production of Th1-related cytokines IFN-γ, CXCL10/IFN-γ induced protein 10 and CXCL9/monokine induced by IFN-γ (MIG)." (PMID 29552008, 2018). "CXCL10/IP-10 and CXCL9/MIG are stimulated by IFN-γ, which together orchestrate the Th1 cellular immune response, known to be important for virus control in influenza infection." (PMID 22022504, 2011). "Our finding of a strong adaptive-immunity related cytokine response (e.g. CXCL10/IP-10, CXCL9/MIG, IL–17A; and IFN-γ) in seasonal influenza but a relatively suppressed response in severe pH1N1 pneumonia is striking." (PMID 22022504, 2011). "Through such approach, it has been reported that different animals (such as primates, ferrets and mice) with influenza infection have been induced extraordinarily high expression of cytokines and chemokines (e.g. CXCL10, CCL2 and CXCL9)." (PMID 21819625, 2011). "PBMCs in seasonal influenza patients were activated and expressed cytokines ex vivo (e.g. IL-6, CXCL8/IL-8, CCL2/MCP-1, CXCL10/IP-10, CXCL9/MIG); their ‘responsiveness’ to stimuli was shown to change dynamically during the illness course." (PMID 22022504, 2011). "Notably, CXCL10, CXCL9, and CXCL11 had previously been found to be upregulated in human nasal epithelial cells after infection with human influenza H3N2." (PMID 41239423, 2025).
influenza (continued). "The expression of interferon response genes STAT1, STAT2, Mx1, OASL2, ISG15, chemokines CCL2, CCL3, CXCL9 and CXCL10, and the frequency of neutrophils (CD45+CD11b+Ly6G+) and CD4+ T cells (CD45+CD4+) were all significantly increased in influenza-infected mice when compared to vehicle controls." (PMID 38750107, 2024). "Decreased expression of the IFN response genes Stat1, CXCL9, and CXCL10 may be due to suppression of the JAK/Stat signaling pathways in response to empagliflozin treatment during influenza infection." (PMID 38112660, 2023). "In an RCT of patients with influenza, combination therapy with oseltamivir and azithromycin showed significant improvement in the levels of inflammatory cytokines, such as IL-6, CXCL8/IL-8, IL-17, CXCL9/MIG, sTNFR-1, and IL-18." (PMID 37243228, 2023). "By day 7, expression of Ccl3, Cxcl9, Cd86, Il-6, Cd80, and Cxcl11 remained elevated in young adult lung in response to H1N1, while expression of Ccl5, Ccl4, and Cd40 remained elevated in response to either strain of influenza." (PMID 34829979, 2021). "CXCL9 and CXCL10 from epithelial cells are strongly induced by influenza infection." (PMID 32817719, 2020). "Notably, when compared with the seasonal influenza group, the Th1-related CXCL10/IP-10 and CXCL9/MIG, and the Th17-related IL-17A were markedly suppressed in cases of severe pH1N1 pneumonia (2–27 times lower; P−values <0.01)." (PMID 22022504, 2011). "In addition, we found that several biomarkers, Cxcl9, Trafd1, and C2 were candidates for evaluating differences between alum-adjuvanted influenza vaccines and nonadjuvanted vaccines." (PMID 25010690, 2014).
autoimmune disease (26 papers, 2013 to 2025). A disorder resulting from loss of function or tissue destruction of an organ or multiple organs, arising from humoral or cellular immune responses of the individual to their own tissue constituents. "Interestingly, CXCL-9, -10, and -11 have been defined as a determinant axis to promote immune cell recruitment and activation, and have been suggested to be the main cause of autoimmune diseases." (PMID 38742118, 2024). "CXCL9 plays an important role in many diseases, including external infection, autoimmune diseases, tumor treatment, lymphoma, and fatty liver disease." (PMID 39940903, 2025). "But given its role in other autoimmune diseases and the relationship with CXCL9 and CXCL10, we also included CXCL11 in our study as a potential pathogenic factor." (PMID 39981245, 2025). "Studies have also suggested associations between the disease activity of autoimmune diseases and serum or BALF CXCL9, CXCL10, and CXCL11 levels in patients with SLE, DM, or SScs." (PMID 33137121, 2020). "In many autoimmune diseases, CXCL9 and CXCL11 are involved in the immune dysfunction in the target organs and excess amplification of the local inflammatory response in patients with various diseases." (PMID 31031647, 2019). "Inflammation of the skin resulting from infections or autoimmune disease drives expression of CXCL9/10/11 and the subsequent recruitment of effector, CXCR3+ T cells from the circulation." (PMID 30320116, 2018). "In a murine model of autoimmune disease the production of CXCL9/10/11 chemokines appears to reduce after 24 days which corresponds to the destruction of the target organs in this condition." (PMID 28253295, 2017). "Chemokines such as CCL17, CCL23, and CXCL9 are frequently upregulated in autoimmune diseases." (PMID 40564127, 2025). "Moreover, recent reviews suggested that the chemokines, CXCL10, CXCL9, and CXCL11, are implicated in the pathogenesis of autoimmune diseases such as autoimmune thyroiditis, T1DM, Graves disease, Thyroid eye disease, and Addison’s disease." (PMID 35242125, 2021). "Moreover, recent reviews suggested that chemokines, CXCL10, CXCL9, and CXCL11, are implicated in the pathogenesis of autoimmune diseases such as autoimmune thyroiditis, type 1 diabetes, Graves disease, Thyroid eye disease, and Addison’s disease." (PMID 34054797, 2021). "CXCL10, also known as interferon γ-induced protein 10 (IP-10), similar to CXCL9, can be secreted by various cells, including monocytes, leukocytes, endothelia, and epithelia, and is up-regulated in numerous diseases, including hepatitis B, tuberculosis, cancer, diabetes, and autoimmune disorders." (PMID 31836011, 2019). "Among the large chemokine and chemokine receptor families, CXCR3 and CXCR3-binding chemokines CXCL10 and CXCL9 and ITAC/CXCL11 are key players in the maintenance and amplification of the autoimmune disease." (PMID 26892362, 2016). "To conclude, markers of CXCR3 pathway, typically involved in autoimmune diseases, were expressed both in SPTL and in control (LEP and EN) cases, but in SPTL, the main source of CXCL9 and CXCR3-positive cells was the malignant, CD8+ lymphocyte infiltrate." (PMID 25928531, 2014). "Studies have shown that CXCL9, CXCI 10, and CXCL11 are involved in the immune dysfunction of target organs and over-amplification of local inflammatory responses at lesion sites in many autoimmune diseases, including IBD." (PMID 36635421, 2023). "The CXCL9/10/11-CXCR3 axis regulates immune cell migration, differentiation, and activation, leading to various immunoregulatory effects in many diseases, such as autoimmune disorders, infections, and cancers." (PMID 35477658, 2022). "The increased expression of CXCL9 and CXCL11 may also excessively activate the hippocampal type Th1 immune and inflammatory response and trigger autoimmune diseases, but the upregulated expression of LYN (ratio: 2.06) eliminated our concerns." (PMID 31031647, 2019).